IL13 (interleukin 13)
Diseases named in the same sentence as IL13 in open-access papers (continued):
Sharing a sentence is not in itself a finding about the gene and the disease.
asthma (continued). "PPARγ agonists also reduce the clinical symptoms in animal models of asthma, a disease which is also thought to be predominantly Th2 type involving IL4, IL5, and IL13." (PMID 17207275, 2007). "YM2 is strongly upregulated in the lung of BALB/c mice during OVA-induced allergic airways inflammation (animal model of asthma), where overproduction of YM2 was dependent on CD4+ T-cells and on signalling of IL-4 and IL-13 through the IL-4Rα subunit." (PMID 19662198, 2007). "It has been shown that several cytokines are elevated in the lung during inflammation in asthma including; interleukin (IL)1β, Tumour Necrosis Factor (TNF)α and IL13." (PMID 17903241, 2007). "Suppressing or upregulating a single molecular route is unlikely to affect asthma because it is caused by a multitude of variables, as demonstrated for IL-4, IL5, and IL-13." (PMID 39981184, 2025). "Consequently, asthma symptoms are exacerbated by the promotion of an increase in CD4+ Th2 cells and the further secretion of cytokines, such as IL-4, IL-5, and IL-13." (PMID 41155294, 2025). "Additionally, glucocorticoids inhibit ILC2 function by suppressing IL-5, IL-13, and IL-9 production via MEK/JAK-STAT signaling pathways, as demonstrated in studies using ILC2s sorted from asthma patients’ PBMCs." (PMID 40355861, 2025). "Anti-IL13 mAbs (tralokinumab and lebrikizumab) reduce TARC levels, but TARC data was not reported in the LAVOLTA I, LAVOLTA II, STRATOS1, or STRATOS2 trials, so there is minimal clinical data regarding anti-IL13 therapy and TARC biomarker utility for asthma." (PMID 40863432, 2025). "Moreover, 1,8-cineole downregulated the levels of pro-inflammatory cytokines, such as IL-1β, IL-4, IL-6, IL-13, IL-17A, and TNF-α, in the BALF of animal asthma models sensitized with ovalbumin, house dust mite, and cigarette smoke." (PMID 40244178, 2025). "First, PDGF‐BB was employed to activate ASMCs; however, other growth factors (e.g., TGF‐β, EGF, and FGF) and inflammatory cytokines (for example, IL‐4, IL‐13, and TNF‐α) may also contribute to ASMC dysfunction in diseases such as asthma." (PMID 40338178, 2025). "Nonetheless, both studies demonstrated that inhibiting IL-13 with tralokinumab led to improvements in pulmonary function among individuals with moderate to severe asthma that was not adequately controlled on medium- or high-dose ICS/LABA." (PMID 40732309, 2025). "Eosinophilic airway inflammation and high IL-4, IL-5, and IL-13 levels define T2-high asthma, which can be allergic or non-allergic, depending on atopy." (PMID 40486460, 2025). "Eosinophil-deficient (iPHIL) mice and mice lacking IL-4/IL-13 producing eosinophils displayed a reduced ILC2 response in HDM- and OVA-induced asthma models." (PMID 40276331, 2025). "Major cytokines involved in asthma include IL4, IL5, and IL13 derived from CD4+ T cells type II." (PMID 40468357, 2025). "In severe asthma, type 2 innate lymphoid cells, which are pivotal in the production of IL4, IL5, and IL13, as well as in T lymphocyte regulation, are markedly increased, along with macrophages, neutrophils, Th1, and Th17 cells, contributing to disease progression." (PMID 40598285, 2025). "Additionally, we explored the correlations between the microbial profiles and inflammatory cytokines known to play key roles in asthma pathogenesis, including IFN-γ, IL-4, IL-5, IL-13, IL-17A, IL-10, and TGF-β1." (PMID 40871265, 2025). "Thus, prolonged treatment with a combination of IL-4 and IL-13 downregulated TSLP secretion and IFNλ1 gene expression, while inducing IFNβ expression, especially in BECs from asthma patients." (PMID 40370530, 2025). "All other macrophage responses to IL-4, IL-13, and combined IL-4/IL-13 stimulation fell within the range of responses seen in donors without asthma." (PMID 41159038, 2025). "In summary, IL-13 may promote ferroptosis and inflammation by activating JAK2/STAT3 and EPAS1, leading to 16HBE cell damage and potentially contributing to asthma progression." (PMID 40165005, 2025).
asthma (continued). "Lebrikizumab and tralokinumab, two anti-IL-13 therapies, were tested in phase 3 clinical asthma trials, but the inhibitors had little to no impact on lung function or reducing exacerbations." (PMID 40136649, 2025). "In murine OVA-asthma, oral administration of EGCG significantly reduced bronchoalveolar eosinophilia, serum IgE levels, and the expression of Th2 cytokines such as IL-4, IL-5, and IL-13." (PMID 41305557, 2025). "Th2‐high asthma is characterized by eosinophilic airway inflammation, also known as type 2 inflammation, primarily mediated by Th2 and ILC2 cells and involving pathways such as IL‐4/IL‐13, IL‐5, and IL‐25/IL‐33/TSLP." (PMID 41310922, 2025). "Specifically, butyrate alleviates asthma by suppressing GATA3 expression and reducing IL-5 and IL-13 secretion from ILC2s, whereas propionate acts through free fatty acid receptor 3 to promote DC and macrophage differentiation, attenuating allergic inflammation." (PMID 41229685, 2025). "Indeed, when used as an add-on strategy in patients with mild to moderate asthma, subcutaneous AIT (SCIT) helps reduce the use of inhaled β2 agonists and decreases type 2 cytokine release (IL5 and IL-13) by PBMCs." (PMID 41145900, 2025). "During asthma remission, mILC2s reside in the small intestine lamina propria via CCR9/CCL25 signaling, but upon viral rechallenge, they migrate to the lungs through S1P/S1PR1-mediated circulation, rapidly producing IL-13 to amplify airway inflammation." (PMID 40636260, 2025). "Subsets of both males and females with asthma were characterized as a mixed granulocytic phenotype due to a moderately high presence of PMN and normal to moderately high eosinophils, higher levels of lymphocytes and the detection of IL-13 and IL-17." (PMID 40821845, 2025). "There is mounting evidence that, irrespective of eosinophilic inflammation, IL-13 mimics many of the characteristics of asthma in mice, including AHR and mucus hypersecretion, and potently stimulates the release of eotaxin from airway epithelial cells." (PMID 40136649, 2025). "These cytokines activate ILC2s producing large amounts of T2 cytokines predominately IL-5 and IL-13, leading to AD when meeting again allergens, and can promote the occurrence of asthma independent of adaptive immunity." (PMID 40236701, 2025). "Biologic therapies that modulate IL-13, TSLP, and ILC2 activation may be particularly beneficial in females with severe asthma, whereas targeting ST2L signaling and modifying Let-7 or miR-712 expression may provide novel treatment avenues for males." (PMID 40508095, 2025). "The secretion of IL-4, IL-5 and IL-13 cytokines by these cells drives chronic inflammation and excessive immune responses in the airways, thereby further strengthening our understanding of TH2-type immune responses in asthma." (PMID 39980673, 2025). "There is evidence that treatment of allergic asthmatics with inhaled steroids was able to reverse the high levels of IL-5, IL-13 and IL-9 produced by ILC2s via STAT3, STAT5, STAT6, JAK3 and MEK signaling pathways, which was accompanied by better asthma control." (PMID 39452061, 2024). "Biologics targeting IgE, IL-5, IL-4/IL-13, and TSLP are crucial in severe asthma treatment." (PMID 38525773, 2024). "Although not currently an approved therapy for asthma, treatment with the anti-IL-13 mAb lebrikizumab reduced subepithelial collagen thickness in patients with uncontrolled asthma, providing further evidence of a role for IL-13 in airway remodelling." (PMID 38609094, 2024). "Furthermore, compared to the Asthma + oe-NC + IDF-11,774 group, the Asthma + oe-MDM2 + IDF-11,774 group demonstrated a significant increase in IL-4, IL-5, IL-13, and IgE levels." (PMID 39061007, 2024). "Alternatively, TJP2, a marker associated with maintenance of tight junctions was significantly (p < 0.05) increased in the IL-13 phenotype, suggesting that HBEC with an asthma-like phenotype may only be able to maintain previously developed tight junctions." (PMID 38706568, 2024).
asthma (continued). "Additionally, research has indicated that a significant decrease in IL-13 levels occurred with a reduction the secretion of eosinophils, which produce large amounts of IL-4 and IL-13, in an OVA-induced asthma mouse model." (PMID 38732497, 2024). "Additionally, we examined the levels of inflammatory cytokines in sputum and found that IL‐5, IL‐6, IL‐8, TNF‐α, IFN‐γ, CCL17, CCL22, CXCL10, CCL4, CCL2, IL‐4, IL‐13, and CCL26 were significantly lower in stable asthma than in acute asthma." (PMID 39508721, 2024). "Contrary to larger levels of histamine uptake in IL-13-treated cells, we observed slower metabolism both with and without the addition of asthma drugs." (PMID 38732251, 2024). "Most asthma biologics that are approved by the US Food and Drug Administration (FDA) target T2 inflammation with specific monoclonal antibodies to IgE, and the IL-5 and IL-4/IL-13 signaling pathways." (PMID 39194521, 2024). "Additionally, compared to the Asthma + Vehicle group, the IDF-11,774 group exhibited a significant decrease in IL-4, IL-5, IL-13, and IgE." (PMID 39061007, 2024). "Type 2-high and type 2-ultra-high asthma again involve IL-4, IL-5, and IL-13, while type 2-low asthma, due to the lack of biomarkers, is described as a type with different mechanisms of disease, including IL-1β, IL-6, or neutrophil infiltration." (PMID 38785919, 2024). "Cytokines produced by NK2 cells, including IL-4 and IL-13, could potentially exacerbate asthma by supporting Th2 responses and inhibiting IFN responses, which may increase the likelihood of asthma worsening triggered by viral infections." (PMID 38216935, 2024). "We did a preliminary study using eosinophils from patients with asthma and found IL-4, IL-13, or TSLP at concentrations up to 10 nM did not induce eosinophil adhesion, O2− generation, or eosinophil degranulation (data not shown)." (PMID 39624446, 2024). "Mast cells play a key role in asthma pathophysiology and airway remodelling through the release of a plethora of cytokines (e.g. TSLP, IL-33, IL-25, IL-4, IL-13 and TGF-β) and angiogenic factors (e.g. VEGF-A), as well as other inflammatory mediators and bronchoconstrictors." (PMID 38609094, 2024). "Taken together, these data provide support for the hypothesis that IL-13–driven increases in TPO in airway epithelial cells could explain, at least in part, the mechanism of formation of mucus plugs in severe forms of asthma." (PMID 38889046, 2024). "IL-13/IL-4/JAK/STAT6 is a key signaling pathway essential to type 2 inflammation and allergies, and strategies to target it have proven effective to treat atopic dermatitis, asthma and to prevent itching." (PMID 39345572, 2024). "Interestingly, the expression of miR-181a in the lung of allergic rhinitis mice reduced the count of eosinophils in BALF and decreased IL-4, IL-5, and IL-13 by targeting high mobility group box 1 (HMGB1), resulting in retarded development of asthma." (PMID 38337625, 2024). "There are other experimental studies on BALF cytology and cytokine response (IL-4, Il-5, IL-13, IL-17 and IFN-γ) in animals only with individual exposure to OVA in OVA-induced asthma; the impact of anti-Il-17 or dexamethasone treatment alone in this model was evaluated." (PMID 38543124, 2024). "The serum levels of TNF‐α (p = 0.025), IFN‐γ (p = 0.011), CCL22 (p = 0.022), IL‐12p70 (p = 0.021), CXCL10 (p = 0.028), CCL2 (p = 0.028), CCL13 (p = 0.024), IL‐4 (p = 0.026), IL‐13 (p = 0.024), and CCL11 (p = 0.028) were found to be downregulated in stable asthma when compared to acute asthma." (PMID 39508721, 2024). "Notably, Th2 cell-related cytokines such as IL-4, IL-5, and IL-13 and Th17 cell-related cytokines such as IL-6 and TNF-α increase in patients with asthma." (PMID 37569846, 2023). "Lastly, the expression levels of IL4 and IL13 were significantly higher in iNKT cells from the allergic asthma patients compared to those from healthy controls and nonallergic asthma patients." (PMID 37917548, 2023).
asthma (continued). "Dupilumab is an IgG4 human monoclonal antibody (mAb) that binds IL-4Ra with subsequent inhibition of IL-4R signaling induced by both IL-4 and IL-13, and down-regulation of TH2 inflammation in a variety of allergic disorders, including atopic dermatitis, asthma, and possibly other allergic diseases." (PMID 36846564, 2023). "A study has found that there were reduced levels of Th1 in asthma, which reduces the levels of certain Th1-secreted cytokines including IFN-γ, and elevated levels of Th2, which can produce large amounts of IL-4, IL-5, and IL-13." (PMID 36846048, 2023). "A basic science study has shown that patients with asthma have more blood ILC2s which produce more IL-5 and IL-13 than healthy controls, indicating that the evaluation of blood ILC2 in patients with asthma might be clinically useful." (PMID 36941691, 2023). "Several cytokines, including interleukin (IL)-4, IL-5, IL-13, IL-25, and IL-33, thymic stromal lymphopoietin (TSLP), and cells such as innate lymphoid cells type 2 (ILC2s), play crucial roles in orchestrating the inflammatory response in asthma." (PMID 37765327, 2023). "Eosinophils produce and secrete fibrogenic factors, such as fibroblast growth factor (FGF), heparin binding epidermal growth factor, IL-4, IL-13, IL-17, nerve growth factor, platelet derived growth factor, and transforming growth factor-β (TGF-β), leading to the development of severe asthma." (PMID 36107283, 2023). "Some other investigational anti-IL-13 monoclonal antibodies, like lebrikizumab and tralokinumab, have also completed phase 3 trials in individuals with uncontrolled asthma, however, have not been approved because inconsistent efficacy in the different trials." (PMID 37189529, 2023). "Pitrakinra, targeting the α subunit of IL-4R, thereby blocking signaling of IL-4 and IL-13, suffered from similar problems to early mepolizumab trials by testing in unselected asthma populations with no clinical efficacy." (PMID 37265457, 2023). "As well, this circumstance also has been described in asthma patients, where some interleukins have been found raised, such as IL6, IL-4, IL-5, and IL-13, secreted from CD4+ lymphocytes, promoting an allergic inflammation which involves a worse prognosis of asthma disease." (PMID 37920579, 2023). "In the presence of type 2 cytokines, such as IL-4, IL-5, IL-9 and IL-13, naive CD4+ T cells differentiate into Th2 effector cells and migrate to the asthmatic airways where they secrete cytokines and propagate cardinal features of asthma." (PMID 37108740, 2023). "Yet it should be highlighted that, as shown in another trial, a single blockage of IL-13 was found to be insufficient to improve lung function in asthma patients who were not getting inhaled steroids." (PMID 37153575, 2023). "Since our study only covered patients that had been diagnosed before 2015, newer asthma medications that directly target the IL4/IL13/IL4R pathway such as dupilimab are not involved." (PMID 37860183, 2023). "The genotype frequencies of ADRB2 rs1042713, IL4 rs2243250, FCER1B rs569108 and IL13 rs20541 were not significantly different between the asthma group and control group." (PMID 38049812, 2023). "We compare peripheral blood (PB) isolated ILC2's proliferative capacity, IL‐5 and IL‐13 secretion and phenotype between healthy without asthma (HC), non‐asthma allergic (NAA), mild asthma (MA) and severe allergic and eosinophilic asthma (SA) subjects." (PMID 37114915, 2023). "T2 high asthma is characterized by reduced lung function, poor asthma control, increased IgE levels, increased responsiveness to ICS treatment and persistent eosinophilic inflammation mediated by cytokines such as IL-4, IL-5 and IL-13." (PMID 40980110, 2023). "As rBmTI-A reduced the concentrations of IL-5, IL-10, IL-13, and IL-17A, CrataBL reduced the numbers of IFN-γ, IL-4, IL-5, IL-13, and IL-17 positive cells in the airways and alveolar walls; both studies used an asthma model." (PMID 37511021, 2023).
asthma (continued). "Furthermore, in asthma and allergic inflammation, a higher STAT3 activation in Th2 cells was induced under treatment with IL-13 (León and Ballesteros-Tato, 2021)." (PMID 38044939, 2023). "In this study, although IL-4 levels were under the detection threshold and IL-13 levels were low in patients with ABPA, their IL-5 levels were significantly higher than those in patients with CPA and were the second-highest after those in patients with asthma." (PMID 35628692, 2022). "And, what is inconsistent with our expectation is that the content of chemokines rather than Th2 cytokines (IL-4, IL-5, IL-13, etc.)surged in the asthma model group, which indicates that the chemokines count for the pathological process of asthma." (PMID 35600943, 2022). "In addition, the concentrations of IL-4, IL-5, and IL-13, as well as IL-1β, IL-6, and TNF-α, were greatly elevated in BALF and lung tissues, especially in lung tissues, of asthma mice, which were suppressed after the treatment of Ferr-1 and/or 3-MA." (PMID 35154576, 2022). "In double IL-4/IL-13 knockout mice, the induction of asthma did not promote tracheal goblet cell hyperplasia and mucin secretion." (PMID 35887041, 2022). "IL-13-specific activity in allergic reactions concerns the modulation of mucus hypersecretion, airway hyperreactivity (AHR), and metaplasia, which are critical events in asthma that lead to the replacement of epithelial cells with goblet cells." (PMID 36430483, 2022). "Asthma is characterised by eosinophilic inflammation of the airway mucosa that is orchestrated by T helper 2 (Th2) and type 2 (T2) innate lymphoid cells (ILC2) through the section of T2 cytokines, including interleukin(IL)-4, IL-5 and IL-13." (PMID 35608088, 2022). "Interestingly, lncRNAs also regulated the expression of cytokines (IL-5 and IL-13), transcription factors (STAT5 and STAT6) and chemokines (CCL17 and CCL22), which mediated Th1 and Th2 inflammatory response in asthma." (PMID 35656293, 2022). "For the ABPA group, the IL-4, IL-13 and IFN-γ+ expression on the metacluster all decreased after allergen exposure; however, the expression of these cytokines barely changed in the metacluster of A.f (+) asthma, Treg of ABPA, and A.f (+) asthma." (PMID 35983066, 2022). "Trials involving lebrikizumab and tralokinumab (anti-IL-13 mAb) demonstrated improvements in lung functions but not in asthma symptoms." (PMID 35663523, 2022). "Several studies suggest that interleukin-13, an important cytokine involved in T2 inflammation, reduces ACE2 expression, and therefore, asthma would not be a significant risk factor for the development of severe COVID-19." (PMID 36186769, 2022). "Furthermore, application of Ferr-1 exhibited a greater inhibitory effect on iron release and lipid peroxidation in IL-13-induced BEAS-2B cells and asthma mice than 3-MA, accompanied with a weaker effect on ferritinophagy than 3-MA." (PMID 35154576, 2022). "Consistently, the expression of SLC7A11, SLC3A2, and GPX-4 was also inhibited, while the level of ALOX5 was enhanced in lung tissues of asthma mice or IL-13-stimulated BEAS-2B cells, further demonstrating the initiation of ferroptosis during the development of asthma." (PMID 35154576, 2022). "Similarly, van der Lans showed that anti-IL-4/IL-13 treatment resulted in a complete and enduring remission of EOM, enabling adequate hearing rehabilitation; concurrent control of the comorbid asthma and CRSwNP was obtained." (PMID 35207196, 2022). "Restraint control of lung inflammation by CD200Fc was also observed in an asthma model where CD200Fc reduced airway hyperresponsiveness and IL-13 level without modulating cell recruitment and eosinophil levels in BALs." (PMID 36591265, 2022). "In asthma, periostin is recognized as a biomarker of type 2 inflammation and periostin (POSTN) gene expression is up-regulated in bronchial epithelial cells by IL-13 and IL-4." (PMID 36010292, 2022).